IGF1 (insulin like growth factor 1)
Diseases named in the same sentence as IGF1 in open-access papers (continued):
Sharing a sentence is not in itself a finding about the gene and the disease.
Hyperinsulinemia (continued). "One of the proposed mechanisms for its anti-neoplastic effects is the reduction of systemic levels of insulin and insulin-like growth factor-1 (IGF-1), thus lowering the mitogenic activity of hyperinsulinemia." (PMID 31345259, 2019). "In cancer and in diabetes mellitus type 2 (DM2), overexpression of these hormone receptors is observed in addition to IGF-1 and hyperinsulinemia, which activates anti-apoptotic and mitogenic routes." (PMID 31284513, 2019). "In fact, hyperinsulinemia in and of itself can be responsible for hyperandrogenism since insulin and Insulin-like growth factor 1 (IGF-1) can act as co-gonadotropins, stimulating ovarian steroid production along with gonadotropins." (PMID 31367382, 2019). "Reductions of insulin sensitivity and compensatory hyperinsulinemia are physiological during puberty, and this partly reflects the effects of increased growth hormone and IGF-1." (PMID 30931082, 2019). "In turn, hyperinsulinism leads to the subsequent activation of the insulin-IGF1 axis that has been theoretically proposed to support the relevance of MetS for WD GEP-NET biology." (PMID 31533348, 2019). "Obesity also leads to hyperinsulinemia and increases IGF1 bioactivity, which, in turn, results in the reduced hepatic synthesis of sex hormone binding globulin (SHBG)." (PMID 30380719, 2018). "Western-type high fat diet can result in, hyperinsulinemia, and over time lead to hyperglycemia due to insulin resistance, and particularly to elevated IGF-1 levels in the circulation." (PMID 29475434, 2018). "TRIB3 is a protein closely related to metabolism, and can be induced by a series of metabolism factors prevalent in DM, such as hyperglycemia, hyperinsulinemia, and IGF-1." (PMID 29367413, 2018). "Increased levels of free fatty acids and hyperinsulinemia have been reported to suppress GH secretion partly by modulating binding proteins of IGF-1 before." (PMID 30206761, 2018). "IGF-1 and hyperinsulinemia were reported to induce PI3K/Akt activity that regulated downstream targets.." (PMID 30359431, 2018). "One likely explanation is the hyperinsulinism in the DM group, which enhanced synthesis of IGF-1 through upregulation of hepatic GH receptors." (PMID 29767287, 2018). "Hyperinsulinemia can increase insulin-like growth factor 1 (IGF-1), which in turn can stimulate liver cell proliferation." (PMID 29379799, 2017). "Insulin-mediated suppression of IGFBP1 and IGFBP2 relieves their inhibitory effect on IGF-1, suggesting one possible mechanism by which hyperinsulinemia potentiates IGF-1 biologic activity." (PMID 28959684, 2017). "In obese Italian children, hyperinsulinemia-related increase in free insulin-like growth factor-1 (IGF-1) levels was considered to enhance bone development and consequently lead to increase in WrC." (PMID 28515034, 2017). "Before stroke, we noted increases in fat mass, serum free fatty acids, insulin, and IGF1 levels in ad libitum‐fed, aged rats that is suggestive of a state of glucose intolerance with hyperinsulinemia." (PMID 28961383, 2017). "In hyperinsulinemia status, the insulin-like growth factor 1 (IGF-1) level increases, which enhances cell proliferation and inhibits apoptosis, thus promoting tumor growth." (PMID 29312558, 2017). "In our own cohort, mostly AGA-born PA girls had early growth acceleration, hyperinsulinism, elevated IGF-1, and decreased SHBG concentrations, and as our current study indicates, also earlier pubertal development." (PMID 29163361, 2017). "Just IR would induce compensatory hyperinsulinemia, and excess insulin would increase insulin growth factor-1 (IGF-1)." (PMID 26770659, 2016). "Instead, Akt and nutrient-sensing mTORC1 were activated early in fatty livers from obese and diabetic mice, attributable to hyperinsulinemia and increased circulating and free IGF-1." (PMID 30873458, 2016).
Hyperinsulinemia (continued). "In particular, chronic hyperinsulinemia can increase the bioactivity of insulin-like growth factor 1, which stimulates tumor development by inhibiting apoptosis and stimulating tumor cell proliferation." (PMID 26934048, 2016). "The mechanisms by which visceral obesity is thought to promote tumorigenesis are manifold, including alterations in adipokine secretion, as well as hyperinsulinemia and subsequent stimulation of insulin-like growth factor-1 axis." (PMID 26968382, 2016). "The mechanisms of T2DM promotes the development of cancer are yet to be investigated, including hyperinsulinemia, high level of IGF-1 and hyperglycemia in T2DM." (PMID 26901856, 2016). "Hyperinsulinemia also stimulates the expression of growth hormone receptor (GHR) in liver to possibly increase liver IGF-1 production by enhanced GHR signalling there." (PMID 26030767, 2015). "Secondly, hyperinsulinemia leads to decreased levels of insulin like growth factor binding protein, which results in elevated levels of free insulin-like growth factor 1 (IGF-1)." (PMID 26134033, 2015). "Hyperinsulinemia leads to increased production of insulin-like growth factor-1 (IGF-1), which activates insulin-like growth factor-1 receptor (IGF-1R)." (PMID 25048361, 2014). "Hyperinsulinemia further stimulates IGF-1 production by upregulating growth hormone (GH) receptors in the liver." (PMID 24367483, 2013). "We thought that in well-growing SGA infants, IR leads to compensatory hyperinsulinemia which in turn increases circulating IGF-1 and possibly IGFBP-3 levels." (PMID 23748063, 2013). "Hyperinsulinemia and resulting increase of IGF-1 can stimulate cellular proliferation, inhibit apoptosis, and promote carcinogenesis." (PMID 23476808, 2013). "Hyperinsulinemia resulting from hyperglycemia promotes carcinogenesis indirectly through increasing circulating free insulin-like growth factor-1 (IGF-1)." (PMID 23431471, 2013). "In particular, visceral fat obesity via this mechanism induces hyperinsulinemia and high IGF-1 concentrations in the blood, which is thought to promote proliferation and division of large bowel cells and induce carcinogenesis." (PMID 24198829, 2013). "Taken together, it is clear that either hyperinsulinemia or increased IGF-1 (or both) can augment tumor growth by signaling through these receptors." (PMID 24280167, 2013). "Hyperinsulinemia is also known to increase circulating IGF1 production, either by up-regulating growth hormone receptor levels or by suppressing IGF binding protein (IGFBP) -1 and -2." (PMID 22226054, 2012). "GLP-1RA decrease chronic hyperinsulinemia and an IGF-1 mechanism could possibly mediate the beneficial oncologic effects that we observed with GLP-1RA in this study." (PMID 41376649, 2026). "The resulting hyperinsulinemia increases the bioavailability of IGF‐1." (PMID 41532033, 2026). "This discrepancy may reflect population differences: the Iraqi cohort was middle-aged and obese, where hyperinsulinemia may sustain IGF-1 despite poor control." (PMID 41393761, 2025). "This correlation is hypothesized to be an effect of proinflammatory cytokines produced by the adipose tissue and chronic exposure to hyperinsulinemia and insulin-like growth factor 1 (IGF-1), which may contribute to carcinogenesis." (PMID 40722648, 2025). "In people with no chronic diseases, IR could be an earlier stage with sustained compensatory hyperinsulinemia, allowing pro-tumorigenic pathways (high insulin/IGF-1, proliferation, anti-apoptosis, low-grade inflammation, oxidative stress) to act more directly." (PMID 41419984, 2025). "Specifically, hyperinsulinemia directly activates insulin receptors and the IGF-1/2 receptors on tumor cells, thereby stimulating the PI3K/AKT/mTOR and rat sarcoma/mitogen-activated protein kinase (RAS/MAPK) signaling pathways to further promote tumor cell growth and survival." (PMID 41567806, 2025).
Hyperinsulinemia (continued). "Additionally, the patient showed elevated levels of IGF-1 at 646.7 ng/mL, likely driven by hyperinsulinemia, which stimulates increased IGF-1 production." (PMID 40428329, 2025). "Factors such as hyperinsulinemia, hyperglycemia, visceral adiposity, estrogen signaling, and IGF-1 pathways, alongside active inflammation, could trigger carcinogenesis and cancer progression, potentially explaining the MetS–EAC link." (PMID 40572713, 2025). "This relationship is believed to be mediated by the proinflammatory cytokines produced by adipose tissue, chronic hyperinsulinemia, and elevated levels of insulin-like growth factor 1 (IGF-I), all of which may facilitate carcinogenesis." (PMID 40002218, 2025). "Possible mechanisms include upregulation of insulin-like growth factor-1 (which has a higher mitogenic and antiapoptotic potency than insulin) via hyperglycemia and hyperinsulinemia, as well as higher levels of proinflammatory factors under chronic inflammation." (PMID 41144600, 2025). "Chronic hyperinsulinemia suppresses hepatic synthesis of insulin-like growth factor binding proteins, thereby increasing free Insulin-like Growth Factor-1 (IGF-1) bioavailability, which subsequently activates IGF-1 receptors (IGF-1R) to promote cellular proliferation and metastatic potential." (PMID 41561157, 2025). "IGF-1 also plays an important role in decidualization, and hyperinsulinemia—along with unopposed E2 and/or HA—may augment the mitogenic activity of IGF-1 in PCOS." (PMID 41155220, 2025). "Furthermore, hyperinsulinemia enhances cytochrome P450c17 activity and increases insulin-like growth factor-1 (IGF-1) bioavailability, further stimulating androgen biosynthesis." (PMID 41377563, 2025). "IGF-1 declined (p = 0.005) in obese mares with hyperinsulinemia and normal insulin." (PMID 40901060, 2025). "Specifically, milk protein may lead to postprandial hyperinsulinemia and alter the growth hormone/insulin-like growth factor-1 (IGF-1) axis, resulting in persistently elevated IGF-1 levels." (PMID 40357063, 2025). "Finally, metabolic stress in the form of hyperinsulinemia promoted cellular IGF1 resistance via downregulation of Igf1r mRNA and protein, through a phosphoinositide 3-kinase/forkhead box O1 (PI3K-FOXO1)-mediated transcriptional mechanism." (PMID 40105689, 2025). "Moreover, hyperinsulinemia can elevate circulating levels of free insulin-like growth factor 1 (IGF-1) by reducing hepatic production of IGF-1 binding proteins 1 and 2, thereby further enhancing tumor growth and proliferation." (PMID 41462693, 2025). "Possible mechanisms includes increased levels of insulin-like growth factor-1 (IGF-1) due to compensatory hyperinsulinemia, which may contribute to tumor development and progression." (PMID 40175445, 2025). "Thus, hypothalamic neurons respond to IGF1 under physiological conditions, and hyperinsulinemia is a novel mechanism that drives cellular IGF1 resistance." (PMID 40105689, 2025). "This state-of-the-art review analyzes the most recent literature data on the multiple interconnected pathways linking DM and OC, including hyperinsulinemia/IGF-1 signaling, chronic hyperglycemia-induced cellular damage, persistent inflammation, immune dysfunction, and oral microbiota dysbiosis." (PMID 41296433, 2025). "Importantly, this study uncovered that hyperinsulinemia induces IGF1 resistance in hypothalamic neurons by downregulating IGF1R and IRS2 through the PI3K-FOXO1 signaling pathway." (PMID 40105689, 2025). "For women, IR and hyperinsulinemia lower Sex Hormone-Binding Globulin levels, increasing free sex hormones, while IGF-1 interacts with insulin signaling and hormone receptors, collectively promoting the development of hormone-sensitive tumors in women, such as breast and endometrial cancer." (PMID 41419984, 2025).
Hyperinsulinemia (continued). "The secondary hypothesis proposes that adipose tissue’s metabolic and hormonal activity promotes carcinogenesis through hyperinsulinemia and insulin-like growth factor-1 (IGF-1) pathway alterations." (PMID 40647438, 2025). "First, IR leads to hyperinsulinemia, which increases IGF-1 levels." (PMID 41210510, 2025). "Hyperinsulinemia and insulin-like growth factor 1 (IGF-1) are potent mitogens that may stimulate the growth of thyroid cells." (PMID 41180194, 2025). "However, ADT also induces hyperglycemia and hyperinsulinemia, resulting in increased levels of IGF-1, further enhancing aberrant growth." (PMID 39954205, 2025). "Prolonged hyperinsulinemia may also lead to an increase in free or bioactive IGF-1 levels, which promotes signaling pathways conducive to tumor development." (PMID 38273418, 2024). "Hyperglycemia due to hyperinsulinemia may improve the biological activity of insulin-like growth factor (IGF-1), which represents an endocrine and paracrine hormone that regulates tissue development and metabolism." (PMID 38785834, 2024). "Hyperinsulinemia increases the levels of IGF-1, which has proliferative and anti-apoptotic effects." (PMID 39200802, 2024). "Thus, the increase in free IGF-1 circulating levels represents an additional mediator through which hyperinsulinemia promotes its mitogenic effects." (PMID 39408212, 2024). "Hence, the level of FF IGFPBs has a direct influence on the availability of IGF-1, meaning that the decreased expression of IGFPBs seen in PCOS patients with hyperinsulinemia results in elevated free IGF-1." (PMID 39519300, 2024). "Besides androgen, insulin and insulin-like growth factor-1 can contribute to hair follicle growth and also hyperinsulinemia, which suppress the sex hormone-binding globulin, a modulator of testosterone bioavailability." (PMID 39336541, 2024). "Considering this standpoint, a hypothesis arises that hyperinsulinemia might potentially trigger a mitogenic impact on osteoblasts, promoting their differentiation through the activation of the IGF-1 signaling pathway." (PMID 38347501, 2024). "There is evidence to suggest that elevated insulin-like growth factor-1 (IGF-1) levels in diabetic patients lead to an increase in cytokine and estrogen levels, an imbalance in adipokines, and hyperinsulinemia, thereby increasing the risk of ovarian cancer and impacting patients’ survival." (PMID 38166541, 2024). "Type 2 DM is characterized by hyperglycemia and is often associated with hyperinsulinemia; both of these states are believed to reduce the production of insulin-like growth factor (IGF)-binding protein-1 by the liver and increase levels of free IGF-1." (PMID 38664791, 2024). "In addition to the diabetogenic effect of GH outweighing the insulin-sensitizing effect of IGF-1, GH and IGF-1 act synergistically to increase insulin secretion, resulting in hyperinsulinemia." (PMID 39735646, 2024). "Resistance-induced hyperinsulinemia can also stimulate the production of insulin-like growth factor 1 (IGF-1), which may promote endometrial cell proliferation and increase the risk of endometrial cancer." (PMID 39767708, 2024). "In addition, animal models showed that reduced IGF1 led to hyperinsulinemia and abnormal glucose clearance." (PMID 38361318, 2024). "This way, IGF-1 contributes to reducing the proinflammatory state produced by hyperinsulinemia." (PMID 36831184, 2023). "Moreover, hyperinsulinemia further increases insulin-like growth factor 1 level, which in turn induces vascular endothelial growth factor expression." (PMID 37876593, 2023). "Long-term consumption of a high-glycemic-load diet results in hyperinsulinemia, which in turn increases the bioavailability of insulin-like growth factor 1 (IGF-1) and directly promotes cell growth, reduces cell death, and stimulates cell division in EC cell lines." (PMID 38137870, 2023).
Hyperinsulinemia (continued). "The second mechanism is the consequence of hyperinsulinemia due to increased BMI, which stimulates the normal growth function of insulin as well as prolonging the duration of the action of insulin-like growth factor-1 (IGF-1)." (PMID 36672434, 2023). "Therefore, a suggestive mechanism is that hyperinsulinemia directly increases cancer progression through overexpressed insulin receptors or indirectly through IGF-1 signaling." (PMID 38004062, 2023). "In addition, hyperinsulinemia is responsible for the increase in the androgen production through both the direct stimulation of insulin receptors and the cross-reaction with Insulin-like Growth Factor-1 (IGF-1) receptors expressed on thecal cells." (PMID 37093453, 2023). "Given that insulin-like growth factor 1 (IGF1) is a powerful stimulator of collagen expression, hyperinsulinemia can promote collagen synthesis by adipose tissue fibroblasts, leading to insulin resistance by activating IGF1 receptors or affecting IGF1 binding protein." (PMID 36902173, 2023). "The combined effects of hyperinsulinemia and elevated IGF-1 levels could thus be a significant contributor to cell proliferation in DAL-induced cancer development." (PMID 37513516, 2023). "Hyperinsulinemia can increase the insulin-like growth factor-1 (IGF-1) expression." (PMID 37346909, 2023). "Possible mechanisms were not clear, which might involve changes in IGF binding proteins (IGFBPs), interference in IGFBP fragments, IGF-1 synthesis or clearance, and/or the effects of hyperinsulinism induced by excess glucocorticoids." (PMID 37441368, 2023). "Many factors have been reported to be involved in the development and progression of cancer in DM, including hyperinsulinemia, elevated free insulin-like growth factor-1 (IGF-1) level, impaired IGF binding protein (IGFBP)/IGF/IGF receptor (IGFR) axis, and inflammatory cytokines." (PMID 36329881, 2022). "Consequently, hyperinsulinemia and subsequent rise in IGF-1 contribute to the development and progression of PC by promoting cellular proliferation and differentiation, inhibiting apoptosis, and enhancing angiogenesis." (PMID 35898377, 2022). "In addition to its effects on estrogen levels, metabolic syndrome can also lead to hyperinsulinemia, which can increase the level of insulin-like growth factor-1 (IGF-1)." (PMID 35756608, 2022). "Apart from the direct mitogenic effects, hyperinsulinemia may also elevate the bioactivity of IGF-1 by decreasing the expression of IGFBPs." (PMID 35296101, 2022). "The significant upregulation of IGF-1 in livers of male offspring of obese dams together with hyperinsulinemia at P21, which has been observed in our prior studies, led us to investigate IGF-1 upstream mediators as well as the insulin and IGF-1 downstream signaling pathway in the liver." (PMID 35628414, 2022). "Chronic inflammation, hyperglycemia, hyperinsulinemia, and abnormalities in insulin/insulin-like growth factor 1 (IGF-1) pathways are some of the proposed molecular mechanisms by which DM and PC are closely related, with emerging evidence showing a positive association between DM and the risk of PC." (PMID 35898377, 2022). "Together with nutrients excess, the increase in free IGF-1 levels may accelerate linear growth and bone age in peri-pubertal period and, with hyperinsulinemia, it would contribute to adrenal and ovarian androgen production." (PMID 35412268, 2022). "Hyperinsulinemia not only reduces the levels of IGFBP-1 but also induces the production of IGF-1." (PMID 36474704, 2022). "Long-term hyperinsulinemia may also result in higher levels of free or bioactive insulin-like growth factor 1 (IGF-1), which can enhance tumor-promoting signaling pathways." (PMID 35145826, 2022). "In insulin-resistant T2DM patients, hyperinsulinemia and free IGF-1 may promote the proliferation of colonic epithelial cells, possibly contributing to development of polyps and tumorigenic effect." (PMID 35742789, 2022).